MC4R (melanocortin 4 receptor)
Diseases named in the same sentence as MC4R in open-access papers (continued):
Sharing a sentence is not in itself a finding about the gene and the disease.
urticaria (1 paper, 2025). A vascular reaction of the skin characterized by erythema and wheal formation due to localized increase of vascular permeability. "The observed remission of urticaria in temporal association with setmelanotide initiation, and recurrence upon drug interruption, provides a strong clinical rationale that MC4R agonism contributed to symptom control." (PMID 41333852, 2025).
uveal melanoma (1 paper, 2021). A melanoma derived from melanocytes of the uveal tract. "The TCGA-UVM data confirmed that MC1R, MC4R, and MC5R were expressed in uveal melanoma, with MC1R exhibiting the highest expression level (data not shown)." (PMID 34436011, 2021).
metabolic disorders (30 papers, 2013 to 2025). "Little is known about the impact of MC4R variants on the biological pathways implicated in metabolic diseases or about the involvement of DNAJC27 protein, which could constitute an important target for understanding the functional role of MC4R in metabolic diseases." (PMID 32733386, 2020). "Furthermore, for a relatively modest difference in BMI (0.4 to 0.9 kg/m2), we observed that β-arrestin-biased GoF alleles in MC4R were associated with a large difference in risk of cardio-metabolic disease outcomes (up to 50% lower risk), more than expected from observational epidemiology studies." (PMID 31002796, 2019). "The clinical research achievements of setmelanotide have introduced new prospects in the field of metabolic disease treatment, and its precision treatment strategy based on the MC4R mechanism paves the way for future drug development." (PMID 40452923, 2025). "Setmelanotide, as a selective agonist of MC4R, provides a new treatment option for metabolic diseases such as Bardet-Biedl syndrome, Alström syndrome, and hypothalamic obesity." (PMID 40452923, 2025). "Our research team also demonstrated that dapagliflozin improved metabolic disorders, normalized the estrous cycle, and restored pulsatile luteinizing hormone (LH) secretion and ovulation in melanocortin-4 receptor knockout (MC4R KO) obese mice." (PMID 39906039, 2024). "Targeting neural MCRs (MC3R and MC4R) is emerging as a therapeutic approach for metabolic diseases and chronic inflammation." (PMID 36291616, 2022). "Remarkably, MC4R is defined as an ideal pharmaceutical target for screening allosteric modulators in order to treat metabolic disorders or maintain controllable body weight for professional athletes such as those in weightlifting, boxing, judo, and artistic gymnastics." (PMID 34759891, 2021). "The detailed mechanisms underlying the role of MC4R variants in the biological pathways underlying metabolic disorders are not well-understood." (PMID 32733386, 2020). "Overexpression of MC4R gene after PCOS induction in the ARC of the hypothalamus may link to metabolic disorders of induced PCOS in the rats." (PMID 34466430, 2018). "Furthermore, a study using PCOS rats models has also found an over-expression of the MC4R gene in the brain hypothalamus which may link to metabolic disorders." (PMID 35144605, 2022). "Taken together, our data reveal an unprecedented opportunity for treating diet-induced metabolic disorders with parallel pharmacological targeting of GLP-1R and MC4R." (PMID 25652173, 2015). "Unlike the clear role of MC3R and MC4R on metabolism, evidenced by the fact that MC4R KO and to a lesser extent MC3R KO mice develop obvious metabolic disorders, its role in reproduction remains uncertain." (PMID 24101924, 2013).
cancer (15 papers, 2008 to 2026). A tumor composed of atypical neoplastic, often pleomorphic cells that invade other tissues. "Further studies are necessary to identify the causal variant near the MC4R gene, as well as the underlying mechanism between the MC4R gene SNP and risk of cancer." (PMID 32899047, 2020). "All studies that evaluated the association between MC4R rs17782313 SNP (or its proxy rs12970134) and cancer risk were included." (PMID 32899047, 2020). "The present study aimed to perform a systematic meta-analysis to clarify the association between the rs17782313 SNP (or its proxy) near the MC4R gene and risk of cancer." (PMID 32899047, 2020). "Before adjusting for BMI, the MC4R rs17782313 SNP risk allele was moderately associated with cancer risk (OR = 1.12, 95% CI = 1.01–1.24) in an additive genetic model." (PMID 32899047, 2020). "The present meta-analysis confirmed the moderate association between MC4R rs17782313 and cancer risk." (PMID 32899047, 2020). "The present study aimed to perform a meta-analysis to clarify the association between SNPs near MC4R and cancer risk." (PMID 32899047, 2020). "The results indicated that MC4R rs17782313 SNP was moderately associated with cancer risk (odds ratio = 1.12, 95% CI = 1.01–1.24)." (PMID 32899047, 2020). "(iii) Acute-phase-protein-levels are elevated in patients developing cancer cachexia, possibly the interaction between one or a combination of these with the variant MC4R leads to the described effects." (PMID 18377640, 2008). "Our primary objective was to evaluate the role of the MC4R Val103Ile polymorphism in the development of cachexia in patients with cancer." (PMID 18377640, 2008). "Meta-analysis of the association between MC4R rs17782313 and cancer risk by cancer type." (PMID 32899047, 2020). "In summary, there might be an association between the MC4R rs17782313 SNP and risk of cancer, which might be mediated by adiposity." (PMID 32899047, 2020). "It appears that the association between the MC4R gene SNP and cancer risk may be mediated through adiposity." (PMID 32899047, 2020). "Thus, the role of the Val103Ile polymorphism of the MC4R for the development of cancer cachexia needs further clarification." (PMID 18377640, 2008). "The mechanism underlying the association between the MC4R SNP and cancer risk remains unclear." (PMID 32899047, 2020). "This strengthens the idea that MC4R inhibition is particularly effective in tumor types that rely on ERK1/2 signaling for survival, a pathway highly activated in BRAF-mutated cancers." (PMID 40004697, 2025). "Future research should focus on advancing preclinical trials in other cancer models and designing early-stage clinical trials to assess the safety and efficacy of MC4R antagonists in humans." (PMID 40004697, 2025). "This study aimed to investigate MC4R as a potential therapeutic target in these cancers using the selective antagonist ML00253764 (ML), alone and in combination with vinorelbine (VNR) and irinotecan (or its active metabolite SN-38)." (PMID 40004697, 2025). "These patterns of alteration in DND1 and MC4R were specific for TGCTs among patterns of alteration found in various cancers." (PMID 37127675, 2023). "It is noteworthy that the ‘pathways in cancer’ were upregulated in activated fibroblasts from livers of MC4R-KO mice fed WD for 20 week, at which they exhibited NASH-like liver phenotypes without HCC development." (PMID 31862949, 2019). "Our data showed that activated fibroblasts exhibited distinct gene expression patterns in each etiology, and that the ‘pathways in cancer’ were selectively upregulated in the activated fibroblasts from MC4R-KO mice." (PMID 31862949, 2019). "A series of experiments demonstrated that cancer cachexia is ameliorated by central MC4R blockade in MC4R knock out mice or by peripheral administration of an antagonist (e.g. agouti-related protein – AGRP) in rats, mice and sheep." (PMID 18377640, 2008).
cancer (continued). "Previous evidence in animal models implicates the melanocortin-4 receptor gene (MC4R) in the development of cancer cachexia." (PMID 18377640, 2008). "The melanocortin receptor 4 (MC4R) emerged as a promising candidate target for cancer therapy." (PMID 40004697, 2025). "A potential approach for targeted therapy in cancer cells could involve the deregulation of MC4R signaling pathways and may be able to interfere with important mechanisms involved in cancer initiation, progression, and metastasis." (PMID 40004697, 2025). "A synthetic MC4R antagonist attenuates cachexia in cancer and CKD animal models." (PMID 39210624, 2024). "The present meta-analysis revealed that the MC4R rs17782313 SNP is moderately associated with risk of cancer, without adjusting for BMI." (PMID 32899047, 2020). "RNA sequencing analysis revealed that activated fibroblasts exhibited distinct gene expression patterns in each etiology, and we focused on fibroblast growth factor 9 (FGF9), which belongs to the ‘pathways in cancer’ selectively upregulated in the activated fibroblasts from MC4R-KO mice." (PMID 31862949, 2019). "There was no publication bias for the association between MC4R rs17782313 and cancer risk." (PMID 32899047, 2020). "We hypothesized that cancer patients with the 103Ile-allele of the MC4R are more likely to develop cancer cachexia than patients without the respective allele." (PMID 18377640, 2008). "Given the ability of MC4R inhibition to suppress tumor proliferation and promote apoptosis, particularly in combination with chemotherapeutic agents, this approach could offer a much-needed targeted treatment option for these challenging and often resistant cancer types." (PMID 40004697, 2025). "Additionally, the role of MC4R inhibition in preventing metastasis remains an intriguing area for exploration, as this could provide new strategies to combat tumor spread and improve overall cancer management." (PMID 40004697, 2025). "Conversely, the expression levels of LEPR, POMC, MC4R, and NEGR1 in two (GBM and PAAD), two (CHOL and LUSC), four (LUAD, LUSC, PCPG, and THCA), and two (CHOL and PCPG) types of cancer were higher than those of the corresponding normal tissues, respectively." (PMID 33299884, 2020). "Although MC4R-KO mice did not develop liver tumors at this time point, the ‘pathways in cancer’ were activated in NASH-fib compared with HSCs and CCl4-fib." (PMID 31862949, 2019). "We examined metabolic gene expression in cancer tissues (HCC), noncancer liver tissues (NASH) from MC4R–KO mice, and normal liver tissue from WT (NC)." (PMID 33681091, 2021). "The expression level of each of MC4R and LEP in several types of cancer tissues did not alter significantly." (PMID 33299884, 2020).
tumor (11 papers, 2007 to 2026). "Furthermore, these results suggest variable responses to MC4R inhibition, potentially associated with differences in downstream signaling pathways or receptor expression levels in each tumor population." (PMID 40004697, 2025). "Together, these pathways highlight the potential of targeting MC4R to disrupt multiple signaling mechanisms critical for tumor progression." (PMID 40004697, 2025). "Together, these effects strengthen the therapeutic potential of MC4R inhibition in tumor growth suppression." (PMID 40004697, 2025). "We chose to test the small-molecule MC4R selective antagonist ML00253764, originally developed by Vos and colleagues, which was previously employed to block tumor-induced weight loss in mice." (PMID 40004697, 2025). "Our findings demonstrate that MC4R inhibition induces apoptosis, blocks tumor growth, and synergizes effectively with chemotherapy drugs, highlighting its potential for combination treatments to improve patient outcomes." (PMID 40004697, 2025). "Taken together, these effects strengthen the therapeutic potential of MC4R inhibition as a strategy for suppressing tumor growth through both pro-apoptotic and anti-angiogenic mechanisms." (PMID 40004697, 2025). "One important avenue for future research is to test the efficacy of MC4R antagonists in combination with immunotherapies, which could significantly enhance treatment outcomes by synergistically targeting both tumor cells and the immune system." (PMID 40004697, 2025). "This suggests a potential role for MC4R in key pathways that drive tumor growth and survival." (PMID 40004697, 2025). "In the current research, we suspected that FTO could act as a tumor suppressor on PCa by regulating the expression of MC4R via a m6A RNA demethylation manner." (PMID 34787056, 2022). "Additionally, understanding the role of MC4R in modulating the tumor microenvironment, particularly its interactions with immune cells, and exploring its combination with immune checkpoint inhibitors, could open new options for therapy." (PMID 40004697, 2025). "Orally bioavailable potent antagonists of the human MC4R (e.g. synthesized compounds of Pyrrolidinones) demonstrated in vivo efficacy in protecting against cachectic symptoms in animal models of tumour-induced wasting and may be a suitable approach for the treatment of cachexia." (PMID 18377640, 2008). "Western blot analysis confirmed the high concentration of MC4R protein in both HT-29 and Caco-2 cell lines compared to HUVEC non-tumor endothelial cells, with two marked bands clearly visible (the upper one probably represents an intermediate glycosylated MC4R)." (PMID 40004697, 2025). "Increased caspase-3 suggests that MC4R inhibition promotes apoptotic pathways, while reduced CD31+ staining indicates altered tumor vasculature, which may limit nutrient supply and tumor progression." (PMID 40004697, 2025). "Long-term treatment with anagliptin for 47 weeks reduced the number of liver tumors and tumor size in MC4R-KO mice, whereas there was no apparent difference in the number of foci between the treatments." (PMID 31969650, 2020).
cardiovascular disease (9 papers, 2014 to 2025). "The main strength of the present study is the use of a genetic instrument to determine the causal effects of common variation in MC4R on cardiovascular disease risk, using data from several large cohort studies, including the CCHS/CGPS and UK Biobank." (PMID 33804309, 2021). "Several studies reported that serum fasting glucose levels and cardiovascular disease are associated with MC4R." (PMID 32807123, 2020). "Previous Mendelian randomization studies, which use single nucleotide polymorphisms (SNPs) associated with BMI as genetic instruments for the exposure, suggested the association between common genetic variation in MC4R and cardiovascular disease is through higher BMI." (PMID 33804309, 2021). "However, the specific effects of common genetic variation in MC4R on cardiovascular disease risk and atherosclerotic plaque phenotype through effects on BMI have not been studied so far." (PMID 33804309, 2021). "Given the protective associations with risk factors for cardiovascular disease (CVD), we investigated associations of MC4R variants with a selected set of CVD outcomes." (PMID 41102563, 2025). "The relationship between MC4R and cardiovascular disease was stronger in men with BMI < 24.75 (OR, 1.40; 95% CI, 1.12–1.74, p = 0.0028) than in subjects with BMI > = 24.75 (p = 0.6461)." (PMID 32807123, 2020). "The relationship between MC4R and cardiovascular disease was stronger in lean men (OR, 1.40; 95% CI, 1.12–1.74, p = 0.0028) than in overweight men." (PMID 32807123, 2020). "Carriers of LoF MC4R variants within the UK Biobank had lower lipid levels and a lower risk of cardiovascular disease, after accounting for body weight, compared to noncarriers." (PMID 41102563, 2025). "In the present study, we aimed to assess the effects of common genetic variation in MC4R on cardiovascular disease outcomes, and we studied whether these effects were influenced by clinical parameters." (PMID 33804309, 2021). "In conclusion, we showed that, common genetic variation in MC4R does not affect cardiovascular disease risk in the general population or in populations at risk for cardiovascular disease, despite a BMI-increasing effect." (PMID 33804309, 2021). "Nevertheless, we consider the outcome of the current study as positive, as carriers of the common BMI-increasing MC4R variant rs17782313-C apparently are not at increased risk of developing cardiovascular disease." (PMID 33804309, 2021). "The relationship of the MC4R gene SNP rs17782313 to cardiovascular disease was also examined." (PMID 32807123, 2020). "Recent studies have reported that the MC4R gene was related to cardiovascular disease." (PMID 32807123, 2020). "In this study, the rs17782313 SNP in the MC4R gene was related to cardiovascular disease in men." (PMID 32807123, 2020). "Thus, common MC4R genetic variation, despite increasing BMI, does not affect cardiovascular disease risk in the general population or in populations at risk for cardiovascular disease." (PMID 33804309, 2021). "However, the interaction between BMI and MC4R (rs17782313) genotype for cardiovascular disease was not significant (p for interaction = 0.0753)." (PMID 32807123, 2020).
genetic disorders (8 papers, 2013 to 2025). "Setmelanotide has shown to be well-tolerated in a phase 2 clinical trial in obese individuals with a rare genetic disorder, and mouse knock-out studies have shown that setmelanotide-associated weight loss is regulated via MC4R, which is mainly attributed to MC4R neurons of the hypothalamus." (PMID 31636637, 2019). "Genetic disorders such as melanocortin-4 receptor (MC4R) deficiency may have an inherent physiological role in these mixed results, as animals with MC4R deficiency have a resistance to weight loss after bariatric surgery." (PMID 23302153, 2013). "A better understanding of the features of genetic diseases can help identify and diagnose an individual's MC4R pathway disease and hyperphagia." (PMID 40528426, 2025).
neurodegenerative disease (4 papers, 2013 to 2025). A disorder of the central nervous system characterized by gradual and progressive loss of neural tissue and neurologic function. "MC4R agonists represent a promising therapeutic avenue, but their efficacy in neurodegenerative disease remains to be demonstrated through well-designed clinical trials." (PMID 41002740, 2025). "Binding of α-MSH with MC4R decreases the intensity of neurodegenerative diseases by stopping the lipopolysaccharide and interferon gamma mediated cell death in astrocytes." (PMID 41002740, 2025). "Collectively, we provide new evidence supporting glial MC4R as a promising target for the development of therapeutics for the treatment of neuroinflammatory and/or neurodegenerative diseases." (PMID 23468969, 2013). "Thus, the finding that the MC4R agonist can decrease microglial TLR4 expression suggests that melanocortins could be useful for reducing TLR4-mediated neurotoxicity in neurodegenerative diseases." (PMID 27359332, 2016). "Activation of melanocortin 4 receptor (MC4R), primarily expressed in the CNS, has been shown to be neuroprotective in neurodegenerative diseases." (PMID 40015967, 2025).
infection (3 papers, 2016 to 2021). The state of being infected such as from the introduction of a foreign agent such as serum, vaccine, antigenic substance or organism. "After 3 days of renal PRV-614 infection (n = 3, phase I), colocalization of PRV-614 and MC4R-GFP immunopositive neurons was seen and largely confined to areas in the sympathetic preganglionic neurons (SPNs) in the ipsilateral intermediolateral cell column (IML) of the thoracic spinal cord." (PMID 27626491, 2016).
inflammation (2 papers, 2022 to 2025). Aberrant reaction of the microcirculation characterized by movement of fluid and leukocytes from the blood into extravascular tissues. "This small molecule MC4R agonist has been shown to attenuate brain inflammation and promote survival." (PMID 36291616, 2022).
kidney disease (2 papers, 2015 to 2021). "Some of these genes are known for rare Mendelian kidney disease where now a new common or less-frequent variant is implicated for affecting general kidney function (PKDH1 with new certainty, NPHS1 and HNF1A in novel loci), a phenomenon observed also in other contexts, like MC4R for obesity." (PMID 34272381, 2021).
bone disorder (1 paper, 2024). "The deletion of the Mc4r gene attenuated bone disorder in Ctns−/− mice." (PMID 39210624, 2024).